RTTN (rotatin)
Description:
Involved in the genetic cascade that governs left-right specification. Plays a role in the maintenance of a normal ciliary structure. Required for correct asymmetric expression of NODAL, LEFTY and PITX2.
Synonyms: DKFZP434G145; MSSP
Tractability: PROTAC: ubiquitination databases record sites on it.
Gene: Protein-coding gene on chromosome 18 (70,003,031 to 70,206,028, reverse strand). Ensembl gene ENSG00000176225.
Subcellular location: Cytoplasm, cytoskeleton, cilium basal body; Cytoplasm, cytoskeleton, microtubule organizing center, centrosome
Subcellular location (Human Protein Atlas): Cytosol; Basal body; Centrosome
Gene Ontology:
Molecular function: protein binding
Biological process: centriole replication; centriole-centriole cohesion; ciliary basal body organization; cilium organization
Cellular component: centriole; centrosome; ciliary basal body
Genetic constraint (gnomAD): Loss-of-function variants: 101 observed, 151.61 expected, observed/expected ratio (o/e) 0.67, 90% interval 0.57 to 0.79. The upper end of that interval is the gene's LOEUF score, 0.79, which puts it in group 3 of 6, group 1 being the genes least tolerant of losing a copy. Missense variants: 1,783 observed, 1,908.4 expected, observed/expected ratio (o/e) 0.93, 90% interval 0.9 to 0.97. Synonymous variants: 718 observed, 725.67 expected, observed/expected ratio (o/e) 0.99, 90% interval 0.93 to 1.05.
Gene-disease validity (ClinGen):
ClinGen rates the evidence that RTTN causes each of these diseases.
microcephalic primordial dwarfism due to RTTN deficiency (autosomal recessive): Definitive.
Homologues: Orthologues: chimpanzee RTTN (98% identical), macaque RTTN (96% identical), rabbit RTTN (87% identical), dog RTTN (85% identical), guinea pig RTTN (84% identical), pig RTTN (83% identical), mouse Rttn (82% identical), rat Rttn (82% identical), zebrafish rttn (49% identical), tropical clawed frog rttn (48% identical), Drosophila melanogaster ana3 (18% identical).
Diseases named in the same sentence as RTTN in open-access papers:
RTTN is named in the same sentence as 23 diseases in open-access papers, as found by Europe PMC text mining. Sharing a sentence is not in itself a finding about the gene and the disease. The quoted sentences say what the papers report.
microcephaly (12 papers, 2016 to 2025). A congenital or acquired developmental disorder in which the circumference of the head is smaller than normal for the person's age and sex. "Altogether, these defects contributed to a marked delay of rosette formation in RTTN-mutated organoids, thus impeding their overall growth and shedding light on mechanisms leading to microcephaly." (PMID 39680576, 2024). "Abnormal brain development pathways and dysfunctional protein mutations are the primary causes of RTTN-related neurological issues, which include microcephaly, congenital dwarfism, mental retardation, ophthalmic symptoms, and epilepsy." (PMID 39336733, 2024). "Intrigued by the TALS-like phenotype of the patient with this RTTN variant, we thought to investigate the associated pathophysiological mechanisms leading to microcephaly." (PMID 39680576, 2024). "Regarding RTTN deficiency, we believe that primary cilium defects contribute, concomitantly to other major defects of cell cycle, to microcephaly." (PMID 39680576, 2024). "All these alterations contribute to NSC pool reduction, thus leading to the microcephaly seen in the patient we describe here and probably, in most patients having RTTN variants." (PMID 39680576, 2024). "Recessive variants in RTTN are associated with a neurodevelopmental disorder with microcephaly and malformations of cortical development known as “Microcephaly, short stature, and polymicrogyria with seizures” (MSSP, MIM #614833)." (PMID 38178912, 2023). "A second canonical splice site variant in a patient with microcephaly resulted from a 3 bp deletion at the end of exon 20 of RTTN, a gene known to be associated with this condition." (PMID 37946251, 2023). "Biallelic variants in RTTN are associated with a neurodevelopmental condition characterized by microcephaly, epilepsy, and brain developmental abnormalities." (PMID 38178912, 2023). "RTTN homozygote mutations are associated with microcephaly, short stature, and polymicrogyria with seizures (OMIM 614833)." (PMID 30258496, 2018). "Homozygous missense mutations in the RTTN gene have recently been identified in patients with microcephaly, intellectual disability, epilepsy and bilateral polymicrogyria." (PMID 26846091, 2016). "Rotatin (RTTN), encoding a large centrosomal protein, is known to be mutated in cerebral malformation syndromes characterized by conditions such as multiple cerebellar gyri, microcephaly, primordial dwarfism, and epileptic seizures." (PMID 40564208, 2025). "Also, Rotatin (RTTN) mutations can lead to microcephaly, as well as polymicrogyria or simplified gyral patterns." (PMID 36139475, 2022). "More recent proteomic studies have identified NMIIA, B, and C as binding partners of rotatin (RTTN), the gene of which is mutated in some cerebral pathologies, such as severe intellectual disability, cortical malformation, microcephaly, and polymicrogyria with seizures." (PMID 32825197, 2020). "Interestingly, the naturally occurring microcephaly-associated mutant, RTTN (A578P), shows a low affinity for STIL binding and blocks centriole assembly." (PMID 28811500, 2017). "Hence, to decipher the underlying cellular mechanisms, we generated unique human neuronal cellular models–iPSC-derived neural stem cells (NSC) and cortical organoids–and unveiled the combination of events that contribute to the depletion of the NSC pool and explain RTTN-associated microcephaly." (PMID 39680576, 2024). "Rotatin (RTTN) is another PPP1R35 interacting protein and is associated with microcephaly and centriole length regulation." (PMID 39136782, 2024). "RTTN contributes to a condition called microcephaly, which prevents the brain from developing properly and results in individuals having a small head." (PMID 30168418, 2018). "Our data show that that PPP1R35 impacts the process of centriole elongation through a close relationship with a known microcephaly protein, RTTN, therefore suggesting that PPP1R35 may be one such candidate microcephaly gene." (PMID 30168418, 2018).
polymicrogyria (5 papers, 2016 to 2023). A developmental brain abnormality characterized by an excessive amount of small convolutions on the surface of the brain and cognitive dysfunction. "Recessive mutations in the RTTN gene were identified as a cause of primary microcephaly, polymicrogyria, and lissencephaly, which exhibit heterogeneous clinical phenotypes and cerebral malformations." (PMID 34207628, 2021). "Recently, a number of RTTN gene mutations have been identified in human patients with primary microcephaly associated with primordial dwarfism, lissencephaly associated with simplified gyral pattern, polymicrogyria associated with seizures, and pontocerebellar hypoplasia." (PMID 34207628, 2021).
Intellectual disability (3 papers, 2016 to 2025). "For instance, RTTN variants are associated with primary microcephaly and primordial dwarfism, often manifesting as intellectual disability and developmental delays." (PMID 40901676, 2025).
brain malformations (2 papers, 2021 to 2024). "Not surprisingly, given the severe brain malformations associated with RTTN variants, the most striking phenotypes were detected in the neural progenitor cells, cultured in 2D or 3D." (PMID 39680576, 2024).
arachnoid cyst (1 paper, 2023). Intracranial or spinal cavities containing a cerebrospinal-like fluid, the wall of which is composed of arachnoidal cells. "Arachnoid cysts in subjects with RTTN variants have been described in several locations, including the posterior interhemispheric region, quadrigeminal cistern, and anterior temporal regions." (PMID 38178912, 2023).
asthma (1 paper, 2018). "The impact of amino acid alterations in PACRG and RTTN proteins, and possible association of the sequence variants with asthma, is of uncertain significance, but their role in ciliary function may be of future interest." (PMID 30324028, 2018).
Cerebellar dysplasia (1 paper, 2023). Cerebellar dysplasia (abnormal growth or development) is defined by abnormal cerebellar foliation, white matter arborization, and gray-white matter junction. "In this study we report a patient with novel biallelic RTTN variants with predicted moderate pathogenic effect, presenting with a milder clinical phenotype characterized by cognitive impairment and peculiar neuroimaging abnormalities, including cerebellar dysplasia." (PMID 38178912, 2023).
congenital heart disease (1 paper, 2025). A heart disease that is present at birth. "Further analysis indicated that GABRP, GJB4, and RTTN were significantly associated with the occurrence of congenital heart disease." (PMID 40901676, 2025).
RTTN also shares sentences with these, for which no sentence is quoted: Primary microcephaly (3 papers); primordial dwarfism (3); developmental delay (2); epilepsy (2); Lissencephaly (2); cardiomyopathies (1); ciliopathies (1); dwarfism (1); eczema (1); Immunodeficiency (1); membranous nephropathy (1); neurodevelopmental disorder (1); Seckel syndrome (1); Taybi-Linder syndrome (1); tethered spinal cord syndrome (1).